IGF1R (insulin like growth factor 1 receptor)
Diseases named in the same sentence as IGF1R in open-access papers (continued):
Sharing a sentence is not in itself a finding about the gene and the disease.
tumor (continued). "However, the mechanisms underlying these tumor-promoting effects of IGF-1R is still not well understood." (PMID 29976975, 2018). "In addition, IGF1R is associated with the metastasis of melanoma at the end of the eye pigment, which is a predictor of this type of tumor metastasis." (PMID 29455664, 2018). "The rationale for this hypothesis lies in the fact that the IGF1R is usually overexpressed in tumors displaying loss-of function mutations of tumor suppressor genes." (PMID 27446805, 2016). "In order to identify transcripts that may be elucidated for the specific effect of IGF1R on CD24+ tumorigenic capacity we screened by qtPCR analysis several transcripts that are associated with tumor growth and metastasis." (PMID 27179633, 2016). "Indeed, patients carrying the G allele of the IGF-1R rs2016347 polymorphism have poorer prognosis compared with those carrying G/T or T/T and has been associated with increased risk of tumor progression and death." (PMID 25743390, 2015). "Moreover, our data suggested that it is the IGF-1R signaling inhibition/receptor down-regulation underlying the anti-tumor effects of metformin." (PMID 26287334, 2015). "For instance, while fractional abundance of ATM, NRAS and IGF1R mutations in the primary tumour was 35%, 20% and 2%, respectively, the prevalence of these mutations in the corresponding plasma samples was 0.05, 0.07 and 0.07%, whereas in the sputum, mutations fractions were 0.04, 0.03 and 0.03%." (PMID 26374070, 2015). "In addition, many neoplasms, including HNSCCs and non-small cell lung cancers (NSCLCs) express high levels of IGF-1R and such overexpression is associated with resistance to therapy 11,12." (PMID 25355701, 2015). "In addition, we found that baseline membranous IGF-1R expression was significantly associated with hormone receptor positivity, lower tumor stage and longer OS, which is in line with previous research." (PMID 25680198, 2015). "IGF-1R has been associated with malignant cell transformation and tumor progression." (PMID 24709958, 2014). "Increased IGF-1R expression levels are associated with higher risk of developing various neoplasms." (PMID 24809702, 2014). "Thus, whereas a number of studies reported that the progression of the tumor from an androgen-dependent to an androgen-independent stage is associated with a major decrease in IGF1R expression levels, other studies showed sustained up-regulation of IGF1R." (PMID 24904527, 2014). "In this study, alterations in the IGF1R gene were assessed by mutational analysis, copy number changes, mRNA expression, and cell surface expression in OS cell lines, human primary tumor samples, and xenograft tumor samples." (PMID 25170759, 2014). "IGF-1R inhibition shows efficacy against prostate cancer, but like most cancer therapies, the effectiveness of this approach will require identification of molecular features that make tumor cells susceptible." (PMID 25344862, 2014). "IGF-1R-targeted therapy in RCC was implicated by an early finding of a greater than 10-fold reduction in tumor growth in mice bearing xenografts of human clear-cell RCC when administered with an antagonist to growth hormone-releasing hormone, which was attributed to a reduction of IGF-1." (PMID 23548153, 2013).
tumor (continued). "To further examine whether miR-140 exerts its tumor suppressor function through downregulation of IGF1R, we performed gain-of-function and loss-of-function analyses." (PMID 24039995, 2013). "Interestingly, effective inhibition of IGF1R activation by ganitumab in vivo was associated with partial downregulation (50% to60%) of total tumor IGF1R." (PMID 23383308, 2013). "However, tumor exposure was biased in favor of the CR domain antibodies due to their selectivity for human IGF1R and superior pharmacokinetic properties associated with their murine IgG1 backbones." (PMID 23383308, 2013). "IGF-1R is implicated in proliferation and survival of many tumor types and is overexpressed in PCa." (PMID 23300537, 2012). "Overexpression of IGF1R is associated with increased survival and proliferation of tumor cells." (PMID 19323821, 2009). "Downregulation of IGF1R was associated with decreased tumour growth in xenograft tumour models." (PMID 19491901, 2009). "As downregulation of IGF1R was associated with decreased tumour growth, AVE-1642 Alexa 680 could be used to predict response post-therapy by fluorescent imaging." (PMID 19491901, 2009). "High-risk patients responded better to AZD5991-1720, an MCL1 inhibitor, while low-risk patients showed improved responses to IGF1R-3801-1738, an IGF1R inhibitor, suggesting that risk stratification may help optimize treatment selection based on tumor-specific vulnerabilities." (PMID 40260244, 2025). "However, consistently to our hypothesis, IGF1R was associated with higher tumor load in the murine model as already seen in the human cohort." (PMID 35574343, 2022). "Likewise, the loss-of-function of certain tumor suppressors can also increase IGF-1R expression." (PMID 33669204, 2021). "In addition, the blockade of IGF-1R processing by small-molecule inhibition of the OST with NGI-1 suggests that tumor therapy strategies that disrupt N-linked glycosylation could potently reduce IGF-1R signaling." (PMID 31101650, 2019). "To assess whether the inhibition of ROCK or IGF-1R was associated with change in adherens junctions as we observed in vitro, we analyzed the expression of E-cadherin and phospho-p120 catenin (Tyr228) by immunoblotting tumor lysates." (PMID 29535813, 2018). "As SUMO1 modification is critical for IGF‐1R's transactivating effects and nuclear receptor is linked to adverse clinical outcome and tumor biological properties, we, here, sought to investigate whether the SUMOylation status of IGF1R may affect cell proliferation." (PMID 28112398, 2017). "Therefore, it will be of interest to establish whether tumor IGF axis polymorphisms represent a favorable predictive profile for treatment with anti-IGF1R therapy in a larger patient population." (PMID 27144430, 2016). "Similarly, miRNA-497 can target insulin-like growth factor 1 receptor (IGF1-R) to repress the tumor growth, which is downregulated and associated with the cell survival, proliferation and invasion, and the sensitivity to chemotherapeutic drugs cisplatin and 5-FU in human CRC." (PMID 26064956, 2015). "Moreover, IGF1R amplification was associated with cellular transformation and tumor progression." (PMID 25110710, 2014). "Furthermore, in preclinical models, IGF-1R signaling demonstrated to interfere with numerous receptor pathways and was implicated in the mechanism to render tumor cell resistant to chemotherapy, antihormonal therapy and to anti-EGFR and HER2 targeted therapies." (PMID 22415797, 2012).
tumor (continued). "Blockade of IGF-1R has been shown to cause inhibition of cancer cell proliferation, survival, and anchorage-independent growth in vitro, to inhibit tumourigenesis, and block tumour invasion and metastasis, and to sensitize cancer cells to chemotherapy and radiotherapy." (PMID 21647361, 2011). "miR-133a inhibits cell proliferation, migration and invasion by regulating genes involved in EMT, such as SOX4, and receptors promoting tumor growth, including IGF1R." (PMID 41596525, 2026). "Alongside IGF1/IGF1R signaling, OPN/CD44 binding activates JAK2 (or FAK)/STAT3 pathways, promoting EMT-associated CSC properties, tumor metastasis, and γ-radiation resistance 28,29." (PMID 41356204, 2026). "In vivo evaluation was performed using severe combined immunodeficient mice bearing xenografts of HER2+ (KPL-4 and Calu3) and IGF1R+ (H322M) tumor models." (PMID 41478661, 2025). "In conclusion, these data demonstrated that IGF1R plasma membrane localisation is more frequent in ACC than in ACA and is associated with a worse tumour behaviour in ACC." (PMID 40038716, 2025). "Moving forward, biomarker-guided clinical trials integrating both tumor-intrinsic and microenvironmental cues-particularly IGF1R phosphorylation status and PTPN9 expression-will be instrumental in refining patient selection and optimizing therapeutic benefit." (PMID 41275311, 2025). "In this study, we investigated how oHSV-induced IGF1R/YAP1 signaling influences feedback pro-survival and proliferative pathways in tumor cells and evaluated the therapeutic potential of combining IGF1R blockade with oHSV and RTx." (PMID 41510300, 2025). "oHSV treatment sensitizes infected primary GBM and BCBM to IGF1R inhibition, enhancing anti-tumor efficacy." (PMID 41510300, 2025). "Knockout of IGF1R in tumor cells under hypoxia led to an increas of LDH release and apoptosis rates, and reduced phosphorylation of PDK1 and AKT." (PMID 40290443, 2025). "Genetic or pharmacologic dampening of IGF1R signaling restores drug response and, in vivo, surufatinib + linsitinib effectively restrains tumor growth; conversely, IGF1R overexpression or Y1165/1166-activating mutants blunt surufatinib efficacy." (PMID 41275311, 2025). "In PDAC, autocrine insulin-like growth factor-1 (IGF-1) and paracrine insulin stimulate the IGF-1 receptor (IGF1R) and insulin receptor (IR) to increase tumor growth and glycolysis." (PMID 40630951, 2025). "One mechanism reported regarding the paracrine interaction between the tumor microenvironment (TME) and tumor cell’s receptor that activates the IGF-1R/PI3K pathway." (PMID 40867316, 2025). "We found that enhanced IGF1R activation occurs exclusively near sites of active viral replication, promoting tumor proliferation." (PMID 41510300, 2025). "More recently, short-term starvation was shown to sensitize non-small cell lung cancer (NSCLC) to PD-1 blockade in vivo by suppressing serum IGF-1 and IGF-1R activity in tumor tissue." (PMID 41184420, 2025). "We first demonstrated that oHSV activates IGF1R signaling in vitro and in vivo, promoting tumor proliferation." (PMID 41510300, 2025). "Our research revealed that knocking out IGF1R in tumor cells and intervening with TMZ significantly increased LDH release and apoptosis rates." (PMID 40290443, 2025). "Studies reported that mevalonate and the intermediate products of the cholesterol biosynthesis pathway induce the expression of IGF1R, which can significantly improve the anti‐apoptotic capacity of tumour cells." (PMID 40874517, 2025). "IGF1R inhibitor NVP-AEW541 showed inhibition of tumor cell growth in NCI-H295R and RL251 ACC models, with an enhanced effect when used in combination with mitotane." (PMID 40145087, 2025). "It is also found that IGF1R promotes tumor cell migration and invasion, as well as T cell exhaustion, with these effects mediated through collagen." (PMID 40679093, 2025).
tumor (continued). "IGF1R inhibitors inhibit tumor cell proliferation and promote apoptosis by blocking related signaling pathways, thus increasing tumor chemotherapy sensitivity, such as OSI-906." (PMID 40290443, 2025). "In H322M tumors, IGF1R-targeting complexes showed rapid tumor-specific accumulation of digoxigenin-Cy5 within 30 minutes, with retention observed for up to 4 hours." (PMID 41478661, 2025). "Overactivation of IGF-1R signaling contributes to tumor growth, metastasis, and therapeutic resistance." (PMID 41294748, 2025). "miR-99a-5p suppresses growth, migration, and invasion by targeting mTOR in RCC and bladder cancer and FGFR3 in PCa, and inhibits tumor growth by targeting IGF1R." (PMID 40161350, 2025). "Collectively, these results suggest that IGF1R blockade enhances oHSV efficacy but remains insufficient for tumor eradication." (PMID 41510300, 2025). "This tumor suppressor function results from the ubiquitination and degradation of insulin-like growth factor 1 receptor (IGF1R) promoted by AIRAPL and requires key players in ERAD, such as p97, FAF2 and BAG664." (PMID 39779978, 2025). "IGF-1, secreted by the liver and by CAFs, activates the RAS/MAPK and PI3K/AKT signaling pathways by binding to the IGF-1R, thereby promoting tumor cell invasion and metastasis." (PMID 41164182, 2025). "IGF-1R neutralizing antibodies and small-molecule inhibitors induced cell death in vitro and tumor regression in vivo." (PMID 40508013, 2025). "Accordingly, inhibition of the IGF-1R signaling on lung cancer cells reduced the proportion of tumor-infiltrating Treg cells and sensitized tumors to anti-PD-1 treatment to a similar extent as short-term starvation." (PMID 38587595, 2025). "Preclinical studies demonstrate that IGF1R inhibitors decrease tumour development, promote apoptosis, and interfere with critical pathways such as PI3K/AKT and MAPK/ERK, which are essential for tumour survival and proliferation." (PMID 39796756, 2025). "We developed TNBCvax, a multi-antigen, multi-peptide vaccine designed to simultaneously target three key tumor-associated antigens: TOP2A, HIF-1α, and IGF-1R." (PMID 40969744, 2025). "IGF1R, a major inhibitor of apoptosis in cancer cells, contributes to metastatic tumor growth and radioresistance." (PMID 40335491, 2025). "LncMLETA1 facilitates tumor metastasis via regulating EGFR and IGF1R expression and its level in patient plasma is correlated with tumor metastasis and a higher TNM stage, indicating its potential as a prognostic biomarker for metastasis of lung cancer." (PMID 39937018, 2025). "This overexpression drives tumor cell proliferation by stimulating IGF1R and subsequent signaling pathways, including the PI3K/AKT/mTOR and RAS/RAF/MEK/ERK pathways, and is often associated with epigenetic changes at the 11p15 locus." (PMID 40145087, 2025). "Unexpectedly, the inhibition of IGF1R signaling induced malignant transformation of tumor foci in PTEN-IGF1RKO and triple-KO mice." (PMID 40115165, 2025). "To address this, we developed TNBCvax, a multi-antigen, multi-peptide vaccine targeting three tumor-associated antigens overexpressed in TNBC: TOP2A, HIF-1α and IGF-1R." (PMID 40969744, 2025). "Administration of an anti-IGF-1R monoclonal antibody (L2-Cmu) in aged mice reduced tumor incidence, suppressed inflammation, and extended lifespan by approximately 9%." (PMID 41294748, 2025). "Recent studies have also demonstrated that miR-145 can be delivered through various nanoparticle platforms and combined with IGF1R inhibitors such as NT157 to achieve synergistic effects on tumor metastasis suppression." (PMID 41463227, 2025). "Collectively, these data identify CAFs as the principal source of IGF1 in the CCA microenvironment and demonstrate that CAF-derived IGF1 activates tumor-cell IGF1R to drive proliferation, migration, invasion, and tumor growth." (PMID 41275311, 2025).
tumor (continued). "As a selective IGF1R inhibitor, OSI-906 inhibits the growth and survival of tumor cells by blocking the tyrosine kinase activity of IGF1R and inhibiting the activation of downstream signaling pathways." (PMID 40290443, 2025). "In the present study, we used this noble SPECT tracer (99mTc-ZIGF1R:4551-GGGC) in imaging GO animal tumor models to evaluate its sensitivity and specificity for targeting IGF-1R." (PMID 39920417, 2025). "IGF1R can affect the tumor microenvironment, and its defective expression reduces tumor growth, proliferation, and also tumor aggressiveness." (PMID 40109870, 2025). "Studies have shown a strong correlation between the abnormal overexpression of IGF-1R and both tumor metastasis and resistance to treatment." (PMID 39920417, 2025). "In contrast, miRNAs that were downregulated in rKGAS cells were shown to regulate tumor suppressor genes including IGF1R, TNFAIP3, and MTOR, suggesting a potential loss of tumor-suppressive signaling in rKGAS cells." (PMID 40952575, 2025). "Tumor cells were seen to have strong membranous IGF1R immunostaining (m-IGF1R 2+) in 7 (5.0%) cases and weak membranous IGF1R immunostaining (m-IGF1R 1+) in 9 (6.5%) cases." (PMID 39775131, 2025). "Preclinical studies have shown that OSI-906 has antitumor activity in a variety of tumor models, especially in tumors with IGF1R overexpression, but it has been less studied in GBM." (PMID 40290443, 2025). "Animal experiments demonstrate that the knockdown of IGF-1R significantly inhibits the formation of CRLM nodules and is associated with an increase in E-cadherin expression in tumor cells." (PMID 41164182, 2025). "A volcano plot revealed that IGF1R was markedly upregulated in tumor tissues and ranked among the top RTKs, expression values for IGF1R were subsequently extracted and presented as a bar plot." (PMID 41275311, 2025). "Our group recently discovered that oHSV infection stimulates insulin-like growth factor 2 (IGF2) secretion, which in turn activates the insulin-like growth factor 1 receptor (IGF1R)-AKT signaling throughout the tumor microenvironment (TME)." (PMID 41510300, 2025). "DIRC3 acts in the nucleus and has been shown to activate expression of the neighbouring insulin-like growth factor binding protein 5 (IGFBP5) gene, which shapes tumour suppression by modulating the insulin-like growth factor 1 receptor (IGF1R) pathway." (PMID 41463281, 2025). "Among the eight significant mutated genes, CDK12, CTNNB1, and MLH1 were tested in both tumor and blood, whereas CTCF, IGF1R, IKBKE, QKI, and TIPARP were only tested in tDNA." (PMID 40227722, 2025). "The IGF-1R is another protein frequently overexpressed in cancers and is involved in tumor cell transformation, growth and apoptosis prevention." (PMID 39960347, 2025). "For example, small molecules and mAb targeting IGF-1R require effective delivery systems to ensure they reach and penetrate the tumor tissue effectively." (PMID 39273251, 2024). "Multiple studies corroborate the pivotal role of the IGF-1/IGF-1R signaling pathway in tumor progression and drug resistance." (PMID 38413558, 2024). "HDAC4 and IGF1R had differentially hydroxymethylated CpGs and increased expression in OPCs across all four of our tumor types." (PMID 38688903, 2024). "Reports from the literature indicate that tumor cells release in the extracellular compartment IGF1R incapsulated in extracellular vesicles, contributing to tumor progression, particularly metastases." (PMID 38892104, 2024). "Higher levels of cytoplasmic IGF-1R have been linked to an increased risk of recurrence following radiotherapy, whereas elevated overall IGF-1R levels correspond to higher tumor grades." (PMID 38686058, 2024). "IGF-1 and IGF-2 are known to enhance BC cell proliferation in vitro, and mouse models show that IGF-1R signaling promotes tumor growth in distant tissues." (PMID 39273251, 2024).